VEGFA (vascular endothelial growth factor A)
Diseases named in the same sentence as VEGFA in open-access papers (continued):
Sharing a sentence is not in itself a finding about the gene and the disease.
tumor (continued). "Furthermore, miR-26a may offer a therapeutic approach for PDAC and other cancers by targeting the E2F7/VEGFA axis, which regulates angiogenesis and tumor growth." (PMID 39859231, 2025). "In addition to biomarkers derived from analysis of tumor tissue, circulating biomarkers, such as levels of VEGFA, soluble VEGFR2 and circulating ECs could be considered to monitor treatment responses." (PMID 38426109, 2024). "Indeed, VEGFA/VEGFC–injection reproduced the changes observed in the tumor-adjacent lymphatics in the WT strain but did not cause fragmentation in the Y949F mutant lymphatics." (PMID 38148112, 2024). "Additionally, VEGFA mRNA contains a binding site for the tumor suppressor miR-383-5p." (PMID 38589413, 2024). "VEGFA may therefore be thought of as a possible target for tumor diagnostics and treatment." (PMID 39457390, 2024). "Although anti-angiogenic drugs are effective, cancer patients treated with VEGFA/VEGFR2 inhibitors are liable to develop resistance likely due to cancer cells finding alternative means to drive tumour-associated angiogenesis (non-VEGFR pathway-driven angiogenesis)." (PMID 38256941, 2024). "Moreover, anti-VEGFA therapy has a significant impact on the tumor microenvironment, which has promoted the development of combined treatment strategies of anti-VEGFA with other tumor immunotherapies such as immune checkpoint inhibitors." (PMID 38716237, 2024). "Regarding VEGFA expression, this gene is substantially enhanced in areas surrounding necrotic foci in tumor spheroids, suggesting a mechanism by which a hypoxic microenvironment might stimulate genes involved in tumor angiogenesis." (PMID 39056705, 2024). "Furthermore, the expression of phosphorylated-JAK2, N-cadherin and VEGFA (by WB) was reduced in tumor tissues, indicating that Oridonin could suppress angiogenesis in vivo." (PMID 38791433, 2024). "Furthermore, when devising treatment regimens, clinicians might tailor therapies based on the VEGFA expression levels in a patient’s tumor cells." (PMID 38716237, 2024). "Moreover, targeting the VEGFA pathway could offer therapeutic benefits, especially in cases where angiogenesis plays a pivotal role in tumor progression." (PMID 39337657, 2024). "Additionally, XPO1+Epithelial regulates endothelial cells via VEGFA-VEGFR1R2 and VEGFA-VEGFR1, which may be associated with promoting tumor vascular production." (PMID 39712016, 2024). "Additionally, 4T-Trap induced tumor hypoxia, resulting in increased VEGFA expression." (PMID 38675493, 2024). "Therefore, it is imperative to re-evaluate the direct cytotoxic effects of bevacizumab on various tumor cells, upon clarifying the relative expression levels of VEGFA and its receptors/co-receptors, as well as the sensitivity of different cells to unit concentrations of VEGFA." (PMID 38716237, 2024). "According to these results, it can be assumed that VEGFA overexpression in tumor tissues could be considered an emerging biomarker to predict response to second-line treatment with Ramucirumab and PTX and to identify GC patients who will benefit from this therapy." (PMID 37893095, 2023). "Also, VEGFA hampers tumor T‐cell development and correlates with PD‐1 expression of CD8+ cells." (PMID 37183363, 2023). "Moreover, high neutrophil count prior to treatment correlates with positive initial response to the vascular endothelial growth factor A (VEGF-A) antibody bevacizumab, and enhanced neutrophil infiltration into tumor tissue is associated with acquired resistance." (PMID 37543576, 2023). "However, the HIF-1α inhibitor 2-ME2 abrogated the increase in VEGFA, MMP2, and MMP9 induced by GSTZ1 deficiency in orthotopic mouse models, revealing that inhibition of HIF-1α with 2-ME2 substantially reversed tumor growth, MVD, and progression in Gstz1-KO mice." (PMID 37906252, 2023).
tumor (continued). "Therefore, it was hypothesized that VEGFA amplification in tumor cells could stimulate not only angiogenesis but also autocrine/paracrine stimulation of tumor growth, thus identifying a subgroup of patients with good response to anti-angiogenesis drugs." (PMID 37893095, 2023). "Therefore, anti-angiogenesis is one of the necessary strategies for the treatment of HCC, and looking for a novel VEGFA regulator that controls the expression of endogenous VEGFA involved in various tumor progression in HCC, would contribute to find a novel therapeutic target for HCC." (PMID 36906615, 2023). "Also, macrophages produce vascular endothelial growth factor A, promoting tumor angiogenesis." (PMID 37009375, 2023). "Tumor diversity seems to be triggered by hypoxia, evidenced by a high positive correlation between tumor diversity and hypoxia-induced genes, including hypoxia-inducible factor 1α (HIF1a) and the direct downstream target, vascular endothelial growth factor A (VEGFA)." (PMID 36980203, 2023). "Moreover, mIHC staining confirmed different expression levels of CD68+ &APOE+ macrophages, FOXP3+ &TNFRSF4+ Tregs, VEGFA, and TGFβ signaling between the tumor microenvironment of the de novo mild OLK and the OLK with moderate to severe dysplasia in clinical study." (PMID 36914617, 2023). "VEGFA is already known for its major role in promoting angiogenesis but plays a key factor in tumour-induced immunosuppression through its pleiotropic effects in driving the proliferation of immunosuppressive cell types, limiting T-cell recruitment into tumours, and promoting T-cell exhaustion." (PMID 35986757, 2023). "Additionally, STAT3 induces tumor angiogenesis via elevating VEGFA levels in various tumors." (PMID 37752569, 2023). "In addition, VEGF has been widely studied in relation to the development of novel drugs against CRC, and numerous reports have demonstrated high expression levels of VEGFA in CRC, which are associated with tumor angiogenesis, metastasis, and poor prognosis." (PMID 36672201, 2023). "Moreover, several studies have indicated that LOXL2 may act as an adaptive response protein to promote VEGFA secretion and tumor angiogenesis." (PMID 37056396, 2023). "Therefore, compared to traditional VEGFA inhibitors, regulating the expression of 383-5p may synergistically inhibit tumor progression from multiple aspects and show better efficacy." (PMID 37592783, 2023). "Furthermore, the silencing of miR-92a could significantly suppress tumor invasion and growth, while the enhancement of miR-29a expression levels could also put a break on metastatic dissemination via targeting VEGFA, LOXL2, and LOX." (PMID 37108330, 2023). "During this process, hypoxia and LA regulate the effects of TAMs on the tumor-associated blood vessels via finely tuning the activation of TAMs and stimulating pro-angiogenic gene transcription in a HIF-α–dependent manner, such as VEGFA, TIE2, and neuropilin-1 (NRP1)." (PMID 38274812, 2023). "In addition, significant downregulation of the pro-angiogenic Vascular Endothelial Growth Factor A (VEGFA) post-C/T in Late Recurrence patients suggests that, in these patients, C/T could counteract the pro-tumor effects often mediated by VEGFA." (PMID 37435088, 2023). "Therefore, we hypothesized that PELP1 suppression reduced the secretion of VEGFA to induce tumor vessel normalization." (PMID 35053547, 2022). "Moreover, CCL5 could increase the number of α-SMAhigh CD90high FAPlow fibroblasts and thus promote tumor angiogenesis by enhancing VEGFA expression and making fibroblasts transdifferentiate into vascular endothelial cells." (PMID 35241150, 2022). "Moreover, LINC00941 was reported that its overexpression could accelerate tumor progression in NSCLC via miR-877-3p/VEGFA axis." (PMID 35938013, 2022). "Thus, it is common to link VEGFA and miRNAs in tumor progression." (PMID 35771149, 2022).
tumor (continued). "The GSEA revealed that the genes correlated with PLCB1, including HEY1, EZH2, VEGFA, E2F3, and STC1, were enriched in angiogenesis, suggesting that the increased expression of PLCB1 might be associated with HCC recurrence via tumor-associated angiogenesis." (PMID 35707353, 2022). "Interestingly, the Ang-2 blockade decreases angiogenesis and inhibits metastasis in mouse tumor models, while the Ang-2 blockade restrains tumor growth and decelerates tumor resistance to anti-VEGFA therapy in various types of cancer when administrated in combination with anti-VEGF drugs." (PMID 36556457, 2022). "In addition, VEGFA, which was involved in tumor angiogenesis, was also downregulated." (PMID 35173528, 2022). "In addition, activation of the AKT/NF-κB pathway might be involved in CCR6-mediated tumor angiogenesis, thereby promoting the secretion of VEGFA." (PMID 36286020, 2022). "Therefore, we speculated that Curcumol may directly regulate the expression level of VEGFA in tumor cells." (PMID 36467048, 2022). "Similarly, therefore, we suggest that S100A4-driven alteration of preexisting vasculature may play a critical role in GBM progression, perhaps by accessing an alternative tumor blood supply in the presence of VEGFA." (PMID 35392912, 2022). "In addition to promoting tumor blood vessel growth, VEGFA also had an immunosuppressive effect." (PMID 36260222, 2022). "Therefore, reducing the production of VEGFA from the source may be better than blocking VEGFA for anti-tumor therapy." (PMID 35626012, 2022). "Additionally, in BMI ≤ 29 group, the VEGFA mRNA level was higher in tumor samples." (PMID 36230822, 2022). "Studies also in VEGFA-overexpressed human tumors and mouse tumor models revealed that apatinib plus PD-1/PD-L1 blockade therapy could alleviate hyperangiogenesis and hypoxia in TME and also alter the immunosuppressive TME into an immunostimulatory microenvironment." (PMID 35392964, 2022). "Thus, we explored whether the LBH gene is correlated with EMT, angiogenesis and VEGFA expression in NPC tumor xenografts." (PMID 34975330, 2022). "Tumor-cell-derived exosomes carrying MiR-21-5p can inhibit the interaction between Krev and capture protein 1 (KRIT1) in HUVECs and activate the β-linked protein signaling pathway by increasing the downstream targets VEGFa and CCND1, thereby promoting angiogenesis and vascular permeability in CRC." (PMID 35681475, 2022). "We also found that Cancer Cells interact with ITGB1 expressed in Fibroblasts, Endothelial Cells, SLC16A7 + Cells, FOXN4 + Cells, Basal Cells, GMP Cells, Monocytes, and NKT Cells through angiogenic signal molecules (VEGFA), which may stimulate tumor growth and metastasis." (PMID 36401283, 2022). "Notably, CAFs promote tumor angiogenesis by secreting VEGFA, and a large amount of VEGFA may result in leaky blood vessels and interfere with the normalization of blood vessels and the inability of immune effector cells to enter the cancer nest." (PMID 35626012, 2022). "Targeting the HIF-1α/VEGFA axis could be a promising strategy against tumor angiogenesis." (PMID 35918758, 2022). "miR-34a directly targets the 3’UTRs of numerous oncogenic mRNAs, including ARAF, CD44, CD117, CDK4, c-Met, cyclin D3, cyclin E2, E2F3, Fra-1, Jagged1, MCM2/5, MET, MYCN, Notch1/2, PIK3R2, PLK1, Smad4, SIRT1/6, and VEGFA, which may contribute to its tumor-suppressive role." (PMID 35961977, 2022). "Then tumor cells could be attracted to the vasculature and come into contact with perivascular tunica interna endothelial cell kinase 2 (TIE2) macrophages that act as conduits for tumor cell escape by expressing VEGFA to increase vascular permeability (B Vendramini-Costa and E carvalho 2012)." (PMID 36313280, 2022). "Finally, inhibition of C4 along with VEGFA inhibition inhibited tumor progression." (PMID 33917524, 2021). "In addition, we found that the expression of VEGFA was significantly up-regulated in tumor tissues." (PMID 33794777, 2021).
tumor (continued). "Moreover, VEGFA can accelerate tumor progression by promoting EMT and metastasis." (PMID 34226531, 2021). "Moreover, our results suggest that circ_0047303 could mediate the upregulation of key angiogenesis‐related genes, including HIF‐1, EIF4E2 and VEGFA in TNBC through sponging the tumour‐suppressive miRNAs." (PMID 34791795, 2021). "However, tumor VEGFA mRNA and MET did have a 2.5±2.67-fold and 3.02±2.16-fold increase in comparing to that in the normal tissue in the patients, while the expression of ERBB2 mRNA showed a slightly decrease in the tumor vs non-tumor tissue (0.93±0.69-fold change)." (PMID 34335943, 2021). "Mir-1, described as a tumor suppressor in many types of cancer, has been reported to be downregulated also in OS cells, in which it directly inhibits the protein expression of VEGFA, with the consequent inhibition of cell proliferation, migration, and invasion." (PMID 33503899, 2021). "Furthermore, our ELISA data indicated that the increased VEGFA, MMP2, and MMP-9 levels upon BATF2 downregulation were significantly impaired after AMD3100 injection, suggesting that these tumour-promoting cytokines associated with MDSCs were also blocked by AMD3100." (PMID 33452462, 2021). "In addition, it has been found that Tregs could secrete vascular endothelial growth factor A (VEGF‐A) in metastatic ovarian cancer, thereby promoting angiogenesis and tumor cell dissemination." (PMID 34977870, 2021). "First, coculture with tumor cells inhibited the expression of M1-related genes encoding IL-6, TNF-α, and IL-1β and increased the expression of M2-related genes encoding CD163, Arg1, IL-10, TGF-β, and VEGFA, as well as expression of TNF-α and CD163 at protein level." (PMID 34093857, 2021). "hsa-miR-29b-3p could control tumour proliferation, invasion and angiogenesis by regulating VEGFA." (PMID 34112125, 2021). "Importantly, these effects could be abolished by adding VEGFA protein, suggesting that IL‐36α suppresses tumor angiogenesis by regulating VEGFA expression." (PMID 33713575, 2021). "The tumor vaccine multi‐epitope Peptibody with bFGF/VEGFA we developed showed significant inhibitory effects on tumor progression and angiogenesis in vivo and vitro experiments, which might be used as a potential therapeutic vaccine for tumor treatment." (PMID 32944017, 2020). "Additionally, the HIF2α transcriptional targets EDN1, EPO, GNA14, and VEGFA were significantly upregulated in the tumor and might also promote tumor progression." (PMID 32235007, 2020). "These biological drugs inhibit either the vascular endothelial growth factor A (VEGF-A) (i.e., bevacizumab), or the epidermal growth factor receptor (EGFR) (i.e., cetuximab and panitumumab), and can be chosen depending on RAS mutation status or primary tumor site." (PMID 33092032, 2020). "It was reported that CAFs influenced the tumor growth and progression, especially invasion and metastasis, via the secretion of many kinds of cytokines such as vascular endothelial growth factor A (VEGFA), CXCL12, Interleukin 6 (IL-6), and the physical remodeling of the ECM." (PMID 32377504, 2020). "Notably, tumor cells express high levels of VEGFA, which has the strongest proangiogenic ability." (PMID 33033240, 2020). "Thus, novel small molecule drugs with good cell and tissue permeability, if able to effectively reduce the VEGFA level in tumor tissue and having few side effects, could be promising therapeutic agents for TNBC." (PMID 32944400, 2020). "Interestingly, although Ang2 blockade attenuated T cell infiltration in neuroinflammation, in the setting of tumor angiogenesis, dual Ang2 and VEGFA inhibition has been shown to promote vascular normalization, thereby facilitating recruitment of T cells into the tumors." (PMID 32149735, 2020). "Here we show that leptin can also induce VEGFA expression in macrophages, suggesting that adipocyte-derived signals may promote tumorigenesis by influencing the tumor microenvironment, as well as the tumor cells directly." (PMID 32318345, 2020).
tumor (continued). "Furthermore, B7-H3 promoted tumor angiogenesis by upregulating VEGFA expression." (PMID 31974361, 2020). "Besides its proangiogenic function, VEGFA promoted tumor dormancy reversal." (PMID 32346064, 2020). "Therefore, blockade of bFGF and VEGFA in a simultaneous manner may be an effective strategy to inhibit tumorigenesis and tumor angiogenesis." (PMID 32944017, 2020). "For example, anti-angiogenic treatment of GBM that blocks vascular endothelial growth factor A (VEGF-A or VEGF), a critical proangiogenic mediator, causes a “normalization” of the vasculature and leads to reduced cerebral edema and improved drug delivery to the tumor." (PMID 32398076, 2020). "Our data also raises the possibility that anti-PI recycling therapy might not only inhibit tumor angiogenesis, but be even more effective against aggressive tumors overexpressing high levels of VEGFA and other pro-angiogenic cytokines that have traditionally been the most refractory to treatment." (PMID 32139674, 2020). "Moving forward, future studies may make use of FISH-flow cytometry to evaluate VEGFA expression among tissue-resident or tumor-infiltrating NK and ILC1 cells, with the goal of determining if there is an ex vivo association between VEGFA expression and the TGF-β-associated ILC1-like phenotype." (PMID 32983113, 2020). "Therefore, we further measured VEGFA concentration in the tumor supernatant by ELISA." (PMID 30755242, 2019). "However, NK cells produce vascular endothelial growth factor A (VEGFA) in tumor tissues, which may enhance the formation of tumor by the way of angiogenesis." (PMID 31531018, 2019). "Therefore, we stained and compared HIF1A and VEGFA in these tumor tissues." (PMID 31312613, 2019). "Moreover, we revealed that EHD1 promoted angiogenesis and tumor growth in a VEGFA-dependent manner." (PMID 31023336, 2019). "Thus, VEGFA may perform different roles in the VM in the different tumour cell types and much should be done." (PMID 30945361, 2019). "Indeed, in the MMTV-PyMT mouse model of spontaneous breast cancer, CCL2, released by either tumor cells or stromal cells at the metastatic lung niche, induces the recruitment of CCR2-expressing iMo, which in turn favor the extravasation of tumor cells, through the release of VEGFA." (PMID 31447834, 2019). "Our data showing that genetic depletion of hypoxia-induced CAIX expression by MDA-MB-231 LM2-4Luc+ cells in vitro results in reduced levels of VEGFA suggests that decreased VEGFA production may be a potential mechanism for the effects of SLC-0111 on normalization of tumor vasculature." (PMID 31319613, 2019). "Unlike known MDSCs, MLACs lack the ability to suppress cytotoxic T lymphocytes and differentiate into tumor-associated macrophages (TAMs), but could still directly facilitate tumor growth and angiogenesis through secreting CCL2, CXCL1/2/5, PAI-1, MMPs, and VEGFA." (PMID 29541408, 2018). "However, little is known about the functional impact of alternatively spliced forms of VEGFA in hepatocarcinogenesis, while changes in isoform expression pattern may have a considerable effect upon tumor development." (PMID 29888133, 2018). "This association was independent of tumor subtype and VEGFA expression." (PMID 29617404, 2018). "In addition to MDSCs, late stage RENCA tumors also generate excess VEGFA which may impact the tumor vasculature and contribute to tumor immunosuppression." (PMID 30388137, 2018). "In addition, inflammatory cells such as CD113b expressing myeloid cells and macrophages were also recruited leading to the formation pre-metastatic niche through increased expression of S100 calcium binding proteins following induction by TNFα, TGFβ and VEGFA secreted by primary tumour cells." (PMID 29506506, 2018). "Finally, both Mo-MDSCs and PMN-MDSCs differentiate into tumor-associated macrophages (TAMs), which facilitate tumor cell growth and survival via secreting IL-6, EGF, and TNF and promote angiogenesis by VEGFA, Semaphorin 4D, and IL-8." (PMID 29541408, 2018).